INS (insulin)
Diseases named in the same sentence as INS in open-access papers (continued):
Sharing a sentence is not in itself a finding about the gene and the disease.
Hyperglycemia (continued). "The incidence of hyperglycemia could be correlated with the changes in the body weight, plasma insulin levels and glucose tolerance in these animals." (PMID 21794120, 2011). "Hyperglycemia is an abnormal metabolic state characterized by a marked insulin defect in muscle." (PMID 19095661, 2011). "Anthocyanins (including cyanidin and delphinidin) have strong antioxidant activity in a liposomal system and could ameliorate hyperglycemia and insulin sensitivity in diabetic mice." (PMID 19965962, 2011). "Fourth, haloperidol may diminish glucose-induced insulin secretion by blocking D2 receptors on pancreatic β-cells, which leads to (postprandial) hyperglycemia." (PMID 21603181, 2011). "It seems possible that decreased plasma ghrelin concentrations in type 2 diabetic patients may be due to a compensatory mechanism against diminished insulin action or against hyperglycaemia." (PMID 21760816, 2011). "Previously, we have shown that intravenously administered bone marrow-derived multipotent mesenchymal stromal cells (MSCs) allows pancreatic islet recovery, improves insulin secretion and reverts hyperglycemia in low doses streptozotocin (STZ)-induced diabetic mice." (PMID 21304603, 2011). "This was the only study in our review to examine treatment of hyperglycemia, and the evidence is inconclusive regarding harm or benefit of the use of insulin infusions in patients receiving PN, furthering the need for more evidence regarding treatment of hyperglycemia in PN patients." (PMID 20811546, 2011). "In addition, GSK-3 inhibitors improve insulin sensitivity in rodent models of diabetes, alleviating hyperglycaemia by decreasing hepatic gluconeogenesis and stimulating glycogen synthesis." (PMID 21253590, 2011). "Therefore, when HbA1c remains higher than 7% after fasting glucose has been normalized or nearly normalized with basal insulin, further improvement requires attention to postprandial hyperglycaemia." (PMID 21679291, 2011). "Whereas hyperglycemia is often thought to be the primary driver of complications progression, there is reason to suspect that impaired insulin signaling could contribute to the retinal pathology observed in diabetic retinopathy." (PMID 22046295, 2011). "The plasma insulin levels displayed non-significant differences between the two groups of animals, though there is a tendency for the GK rats at this age to exhibit elevated circulating insulin consistent with hyperglycaemia and impending diabetic state as the animals get older." (PMID 21490936, 2011). "Because this regimen may fail to control post-meal hyperglycaemia, an alternate approach is to use prandial + basal insulin as a mixture of short- or rapid-acting and basal insulin in various ratios." (PMID 21517955, 2011). "Diabetic retinopathy is characterized by numerous retinal defects affecting the vasculature and the neuro-retina, but the relative contributions of the loss of retinal insulin signaling and hyperglycemia have never been directly compared." (PMID 22046295, 2011). "All HFD animals developed hyperglycaemia with elevated plasma insulin." (PMID 21347323, 2011). "Fiber may slow the absorption of carbohydrates, thus reducing possible hyperglycemia and serum insulin levels from carbohydrate-rich foods and increasing insulin sensitivity." (PMID 22104320, 2011). "al found that the postprandial hyperglycemia and insulin sensitivity varied among different ethnic groups, and that lean, young South East Asians had the highest postprandial glycemia and the lowest insulin sensitivity in response to a realistic carbohydrate load." (PMID 21773021, 2011). "Insulin therapy is the preferred method for treating hyperglycemia in the hospital." (PMID 23882328, 2011).
Hyperglycemia (continued). "Factors disturbing ER function affect the fate of glucose and promote hyperglycemia through insulin resistance, stimulation of hepatic glucose production and suppression of glucose disposal, and gene-activating therapy can restore normal glucose-insulin homeostasis." (PMID 21568932, 2011). "From our previous data, we did not observe increased levels of ROS in POKO mice at this age; however nitrogen species under pathophysiological conditions such as chronic hyperglycemia could result in insulin secretion dysfunction in POKO islets." (PMID 22208362, 2011). "Correctional insulin may be used judiciously as a supplement to basal and meal-time insulin, in order to correct pre-meal hyperglycemia." (PMID 23882328, 2011). "Interestingly, similar to PKCδKO mice, these mice show improved recovery from streptozotocin-induced hyperglycemia, which has been attributed to an increased regeneration of insulin-producing cells." (PMID 22216119, 2011). "In experimental groups in which sustained hyperglycemia correction was attained (diabetic + 1xMSCs, diabetic/insulin + 1xMSCs, diabetic/insulin + 2xMSCs) a significant increase in pancreatic islet number and an improvement in endogenous insulin production were observed." (PMID 21304603, 2011). "On the other hand, hyperglycemia due to insulin resistance has been reported in human sepsis." (PMID 21470423, 2011). "Hyperglycemia in Ran transgenic mice was associated with reduced blood insulin levels, compared to non-transgenic littermates." (PMID 22114719, 2011). "The capacity of insulin to activate Akt signaling cascade is impaired in hyperglycemia." (PMID 19965962, 2011). "Hyperglycemia impairs glucose and insulin regulation of NO production where glucose inhibits NO production which may occur through AMP-activated protein kinase inhibition in ventromedial hypothalamus neuron." (PMID 21569551, 2011). "The objective of the present study was to investigate the occurrence of hyperglycemia in relation to the insulin response and exogenous factors, such as glucose intake and drug use, in a homogenous group of critically ill children with meningococcal sepsis or meningococcal septic shock or both." (PMID 21276273, 2011). "Hyperglycaemia is a common finding in critically ill children in the first 48 hours of their admission and is usually due to resistance or a decreased sensitivity of the tissues to insulin." (PMID 22163211, 2011). "Chemical or biological compounds such as macelignan, chromium-phenylalanine, PBA (phenyl butyric acid) or TUDCA (tauroursodeoxycholic acid) or molecular chaperon have been shown to inhibit ER stress and enhance insulin sensitivity, thereby normalizing hyperglycemia." (PMID 21375727, 2011). "A mixed nutrient meal elicit a more robust insulin response and may be more physiologic measure of maternal hyperglycemia and subsequent macrossomia." (PMID 21831283, 2011). "Although several approaches are presently available to reduce the hyperglycemia including insulin therapy, and treatment with sulfonylureas, metaformin, and α-glucosidase inhibitors, unfortunately, all of these therapies have limited efficacy and various side effects." (PMID 22116046, 2011). "In the present study we employed a double approach using phloridzin and local ocular insulin administration to dissect the effects of decreased retinal insulin signaling and systemic hyperglycemia and their respective roles in the pathophysiology of diabetic retinopathy." (PMID 22046295, 2011). "It has been well known that hyperglycemia and insulin could modulate Akt activity in diabetic renal tissue." (PMID 19965962, 2011). "However, we cannot exclude the possibility that the metabolic alterations observed in the adult offspring of CPS exposed mothers were a consequence of prenatal hyperglycaemia exposure following reduced glucose tolerance and insulin sensitivity of the mother." (PMID 21494686, 2011).
Hyperglycemia (continued). "The third child had uncontrolled hyperglycemia despite strict insulin and diet therapy." (PMID 21274314, 2010). "Two hours after injection, hyperglycemia is observed with a concomitant drop in blood insulin." (PMID 22043204, 2010). "Estimating of post-load hyperglycemia and parameters such as plasma insulin level could better clarify the relationship of post-load hyperglycemia and cardiovascular events after AMI." (PMID 21070650, 2010). "In animal models and a limited number of human studies carried out so far, polyphenols and foods or beverages rich in polyphenols have attenuated postprandial glycemic responses and fasting hyperglycemia, and improved acute insulin secretion and insulin sensitivity." (PMID 20480025, 2010). "Also, it is not clear if this anti-inflammatory effect is a direct effect of insulin on cells of the immune system or if the reversal of inflammation occurs secondary to normalization of hyperglycemia and other metabolic abnormalities." (PMID 20463885, 2010). "Type two diabetes results from decreased insulin sensitivity and hyperglycemia." (PMID 22254008, 2010). "However, a small counter-regulatory increase in insulin production was sufficient to prevent an incipient hyperglycaemia." (PMID 20948968, 2010). "Excessive HGP is a major contributor to both fasting and postprandial hyperglycaemia and is suppressed by insulin by inhibiting the expression of gluconeogenic enzymes, namely phosphoenolpyruvate carboxykinase 1 (Pck1), fructose-1,6-bisphosphatase (Fbp1) and glucose-6-phosphatase." (PMID 20977585, 2010). "Phenotypic differences in body composition were also linked to changes in plasma metabolite concentrations, as plasma glucose and insulin concentrations were elevated in the UNAD group (mainly in females) demonstrating hyperglycaemia, compared to the two other groups." (PMID 20482891, 2010). "Overall, chronic hyperglycemia and compensatory increase in insulin secretion ability of pancreatic β cells and islet hypertrophy may result in increased production of PANDER in islets." (PMID 21113299, 2010). "If dieting errors are corrected by keeping similar amounts of carbohydrates at each meal and postprandial hyperglycemia still occurs, it is suggested to introduce fast-acting or ultrafast-acting insulin before the "troublesome" meal, instead of an additional NPH insulin dose." (PMID 20718958, 2010). "Here we sought to determined a possible functional parallel between the enlargement of islet size in response to taurine supplementation, the number of islets, the resistance to glucose-induced hyperglycemia and the levels of the three main pancreatic peptides: insulin, glucagon and somatostatin." (PMID 20804628, 2010). "Metabolic disorders that make a patient prone to hyperglycaemia are a subject of speculation, but almost certainly include pre-existing increased insulin resistance and dysfunction of beta cells." (PMID 20615210, 2010). "To determine the underlying mechanisms whereby Men1 ablation prevents STZ-induced hyperglycemia, we determined cell composition in islets, BrdU incorporation by beta cells, islet size, and circulating insulin levels in control and Men1-excised mice 4 weeks after STZ injections." (PMID 21318185, 2010). "A problem that is often encountered is a patient that is already on insulin and has poor glycaemic control, either due to problems with hypoglycaemia or weight gain with increasing doses of insulin, or simply due to failure of hefty doses of insulin to reduce the hyperglycaemia." (PMID 27713366, 2010). "Indeed, during euglycaemic clamp, an increase in insulin levels leads to suppression of ghrelin levels and is remained suppressed during subsequent hypoglycemia and even fell further during following hyperglycaemia." (PMID 20700400, 2010).
Hyperglycemia (continued). "By adjusting insulin delivery rate in advance, it might be possible to prevent hyperglycemia induced by glucose intake (food) or drugs (glucocorticoids), but no study addressed this question in critically ill patients." (PMID 20840773, 2010). "Such modeling may provide intelligent/directed therapy recommendations, guidance, and ultimately automation, in the near future as a means of providing optimal patient safety and care in the provision of insulin drips to prevent hyperglycemia and hypoglycemia." (PMID 20828400, 2010). "Insulin may be neuroprotective as it can prevent hyperglycaemia-induced oxidative stress and apoptotic cell death." (PMID 20374626, 2010). "Acarbose reduces both postprandial hyperglycemia and hyperinsulinemia, and thereby may improve sensitivity to insulin and alleviate stress on pancreatic β-cells." (PMID 20334663, 2010). "Hence, it is unlikely that there is any significant effect of exogenous insulin or hyperglycemia on Treg apoptosis." (PMID 19654878, 2009). "However, this study establishes the concept that GLP-1 as sole therapy, or in combination with insulin, has the potential to manage hyperglycaemia in the critically ill." (PMID 19439067, 2009). "Moreover, overt diabetic mice treated with the purified mCD4CD62L Tregs showed an elimination of hyperglycemia and a marked improvement in insulin production, which is correlated with a significant increase in β-cell mass and proliferation of β cells." (PMID 19156219, 2009). "Patients with respiratory and cardiovascular failure appear to have more severe CIH compared with those with respiratory failure only, as evidenced by more rapid onset of CIH, higher degree of hyperglycaemia, longer duration and higher insulin needs to restore normal glycaemic levels." (PMID 19245691, 2009). "These include inadequate glycemic control with other treatment options, marked variability in glucose on a day-to-day basis, a history of hyperglycemia unawareness, a need for flexibility in lifestyle, pregnancy, insulin sensitivity and low insulin requirements." (PMID 21821504, 2009). "Insulin dysregulation and hyperglycemia play an important role in neurodegeneration." (PMID 21416014, 2009). "However, insulin pre-treatment completely prevented the development of STZ-induced hyperglycemia in rats." (PMID 20407554, 2009). "Our hypothesis is that maternal hyperglycaemia stimulates fetal insulin production, which has a positive effect on fetal growth." (PMID 19385960, 2009). "Tissue-protective properties of insulin are expanded well beyond its control of hyperglycemia." (PMID 19536295, 2009). "Lastly, with this study design, it is not possible to determine precisely the extent to which the expression profile associated with the T1D phenotype could be mediated by possible secondary effects of insulin or hyperglycemia." (PMID 19654878, 2009). "Methodology: Rats were divided in three main groups depending on blood glucose levels into group-1: having normal BGLs (80 – 110mg/dl), group-2: diabetic rats with hyperglycemia (BGLs > 350mg/dl) and group - 3: insulin treated diabetic rats having BGLs <103 mg/dl." (PMID 21593974, 2008). "Although treatment of hyperglycaemia improves outcome, insulin might have harmful effects by inducing hypoglycaemia and a metabolic crisis caused by low cerebral glucose levels." (PMID 18218076, 2008). "Increased expression of UCP-2 and decreased expression of UCP-3 in humans with chronic hyperglycemia may contribute to impaired glucose-stimulated insulin secretion." (PMID 18167556, 2008). "Parenteral nutrition reduces endogenous glucose production and promotes hyperglycemia in critical illness, effects which may be modulated by insulin administration." (PMID 18312617, 2008). "However, the ICU patients were treated with insulin therapy to overcome hyperglycemia and experimental hyperinsulinaemia has been shown to increase the expression of some oxidative phosphorylation genes." (PMID 18997871, 2008).
Hyperglycemia (continued). "We also hypothesised that the in vitro induced cells would differentiate further into glucose responsive insulin producing cells under the hyperglycaemia with right supporting environments in the SCID mice, based on our previous observation." (PMID 18628974, 2008). "The patient required insulin therapy for hyperglycaemia within 24 h of stopping levofloxacin." (PMID 18644072, 2008). "Once hyperglycaemia has been controlled, the average nutrition rate recommended by the protocol increases, generally as patient condition improves and carbohydrate tolerance increases, whilst average insulin administration rate remains relatively constant." (PMID 18412978, 2008). "While it should be acknowledged that everyone is different with respect to the balance of basal and postprandial hyperglycaemia, further movement towards target HbA1C may subsequently be best achieved by adding meal-time insulin injections." (PMID 19143853, 2008). "The only commonality ofthe two disorders is hyperglycemia.Although hyperglycemia remains a prominent factor in the pathogenesis ofthe chronic complications, probably equally important is the role of insulin orlack thereof together with its prime assistant C-peptide." (PMID 18437223, 2008). "Exenatide (ByettaTM), the first such compound to be licensed by the European Medicine Agency (EMEA), enhances glucose-dependent insulin secretion, regulates glucagon release, and delays gastric emptying thereby reducing hyperglycaemia in a similar manner to GLP-1." (PMID 18694484, 2008). "However, the precise cellular and molecular mechanisms of hyperglycemia and insulin therapy have yet to be fully characterized." (PMID 18710523, 2008). "In addition, insulin inhibits hyperglycaemia-induced oxidative cell damage, thereby positively influencing various intracellular signaling cascades." (PMID 18680584, 2008). "Early goal-directed therapy for severe sepsis and septic shock, lung protective strategy for acute lung injury (ALI), control of hyperglycemia using intravenous insulin and the use activated protein C for severe sepsis reduce the morbidity and mortality of critically ill patients." (PMID 17686165, 2007). "Although we hypothesised that the POKO mice would become insulin resistant, the degree of hyperglycaemia in these animals was in excess of what we expected." (PMID 17465682, 2007). "MODY3 patients have a defect in insulin secretion but no obvious hyperglycemia probably related to massive urinary glucose loss." (PMID 18074013, 2007). "It is possible that corticosteroid treatment may induce hyperglycemia and that the frequency of insulin use may increase with corticosteroid exposure." (PMID 17306016, 2007). "Hypoglycemia and hyperglycemia are also seen with insulin, IFG-1, and HGH, respectively." (PMID 17364003, 2007). "Thus, postprandial hyperglycaemia reduces pancreatic B-cell function, and results in impairment of insulin secretion." (PMID 17257277, 2007). "Indeed, a permanent hyperglycemia requiring insulin therapy developed in five of the seven TNDM patients who were older than 8 years of age in a French cohort." (PMID 17349054, 2007). "Four evidence-based protocols (lung protective strategy for acute lung injury, activated protein C for severe sepsis/septic shock, intravenous insulin for hyperglycemia control and a protocol for sedation/analgesia) were introduced in the MICU between February 2002 and April 2004." (PMID 17686165, 2007). "Future experiments will also determine whether L-arginine can stimulate insulin secretion and thereby correct hyperglycemia in diabetic animals expressing insulin in liver." (PMID 17941991, 2007). "However, chronic hyperglycaemia impairs glucose-induced insulin secretion and insulin gene expression." (PMID 17257277, 2007). "Postprandial hyperglycemia is associated with lower circulating leptin whereas resistin and adiponectin are not altered in slim, insulin-sensitive probands." (PMID 17311679, 2007).